RORB (RAR related orphan receptor B)
Diseases named in the same sentence as RORB in open-access papers (continued):
Sharing a sentence is not in itself a finding about the gene and the disease.
cancer (19 papers, 2013 to 2025). A tumor composed of atypical neoplastic, often pleomorphic cells that invade other tissues. "Moreover, the effects of some melatonergic genes varied across cancer types; for example, RORB was associated with unfavorable survival for KIRC and STAD, while it was associated with favorable survival for COAD and LUSC." (PMID 33842355, 2021). "RORA and RORB are also transcription factors which share high sequence homology, with 4% and 6% of their studied variants showing a statistically significant association with cancer risk, respectively." (PMID 28177907, 2017). "In contrast, some melatonergic genes were significantly overexpressed during cancer progression and were opposite to their differentially expressed status between cancerous and normal samples (e.g., RORB in COAD, KIRC, and STAD; CALM1 in BRCA; CYP1A2 in LUSC)." (PMID 33842355, 2021). "This circadian-cancer link was confirmed in a meta-analysis showing association between risk of cancer and variants in NPAS2, RORA, RORB, and CLOCK." (PMID 31303884, 2019). "To further clarify the effect of RORβ on CCICs, we observed the tumorigenicity in vivo, the change in the colosphere number and the ratios of CD44 + CD24+ cancer-initiating cells in cells with overexpression of RORβ." (PMID 28137278, 2017). "The genes that contributed the most to the overall association with cancer risk were NPAS2, CLOCK and RORs (RORA and RORB)." (PMID 28177907, 2017). "Specifically RORB expression was highly down-regulated in cancers including both serous and endometrioid types." (PMID 23785665, 2013). "Because both RORB and its SNPs have been demonstrated to regulate cancer growth 17, 24 and because RORA levels are significantly higher in individuals with OSCC 18, RORB SNP variants may be corrected with the clinical status of OSCC." (PMID 39744492, 2025). "For example, there is research showing that clock gene variations, particularly to NPAS2, CLOCK, RORA, RORB, and PER3, may contribute to small but statistically significantly elevated cancer risk." (PMID 36387255, 2022). "Some studies suggest that RORα is a tumor suppressor and a potential therapeutic target for BC; and based on the limited researches on RORβ in cancer, RORβ might be a tumor suppressor as well." (PMID 29904382, 2018). "Very little is known about the role of RORβ and RORγ in cancer." (PMID 26878025, 2015). "Among 7912 samples across 18 cancer types, we interestingly observed that the majority of the clock control gene, such as HLF, KLF10, FBXL3, TEF, RORs (RORA, RORB, RORC), and NR1D2, are down-regulated in a wide range of cancers." (PMID 36895015, 2023). "Whereas there are nine rhythm genes (MTNR1B, NR1D1, RORB, RORA, OPN4, C1orf51, PROK2, SERPINE, and EGR3) that are differently expressed in the high and low MSI group in more than 1/3 cancer types." (PMID 31927791, 2020). "The second ROR family member, RORβ, is a less-discussed molecule in cancer and does not act downstream of cholesterol." (PMID 36316442, 2022). "In order to achieve a systematic understanding of circadian clock in cancer, we define a core subset of clock family genes including 7 positive regulators (CLOCK, NPAS2, ARNTL, ARNTL2, RORA, RORB, and RORC) and 7 negative regulators (PER1, PER2, PER3, CRY1, CRY2, NR1D1, and NR1D2)." (PMID 31708917, 2019). "As discussed in this review, the protumor or antitumor effects of RORα and RORβ in cancer have not been intensively explored, requiring further study and evidence." (PMID 29904382, 2018).
tumor (17 papers, 2017 to 2025). "Due to limited case number, the association of RORB expression with tumor cell ploidy and prognostic values of RBM10/RORB axis in NB warrant further investigation via a larger series of cases with longer follow‐up duration." (PMID 40899609, 2025). "We observed that core clock genes, PERs, CRY2, CLOCK, NR1D2, RORA and RORB exhibited global patterns of somatic loss and downregulation across multiple tumour types." (PMID 31014368, 2019). "Consequently, more frequent follow-up is recommended for patients with OSCC with RORB SNP rs10781247 and rs3750420 variants for monitoring potential adverse tumor progression." (PMID 39744492, 2025). "Pre‐clinically, treatment with inhibitory peptide blocking RBM10‐RORB interaction suppresses lysosomal biogenesis and aggressive features of tumor cells, highlighting the biological significance of RBM10/RORB/NF‐κB axis in NB progression." (PMID 40899609, 2025). "Meanwhile, therapeutic potential and toxicity of RIP‐12 or melatonin in regulating RBM10/RORB axis deserve studies by using patient‐derived tumor xenografts or immune‐competent mice models." (PMID 40899609, 2025). "The RAR-related orphan receptor beta (RORB), a regulator of the circadian rhythm, has been implicated in certain neoplasms." (PMID 39744492, 2025). "Some studies have shown that RORB acts as a tumor suppressor." (PMID 32211020, 2020). "The expression levels of RORB in other tumors as well as the molecular mechanisms of how RORB affects tumor formation and progression are still unknown." (PMID 28177907, 2017). "RORB regulates Wnt pathway activity, which may be correlated with tumorigenesis and tumor stages." (PMID 32666718, 2020). "Meanwhile, RBM10 physically interacts with and represses RORB transactivation in liquid condensates, and possesses oncogenic properties in facilitating tumor growth and aggressiveness, indicating the crucial roles of RBM10/RORB/NF‐κB axis in NB progression." (PMID 40899609, 2025). "The tumor with EWSR1::RORB fusion showed a morphologic appearance that was not distinctive of any specific type of round-cell sarcoma." (PMID 38339014, 2024).
neurodevelopmental disorder (5 papers, 2019 to 2025). A behavioral and cognitive disorder with onset during the developmental period that involves impaired or aberrant development of intellectual, motor, or social functions. "The mechanisms by which RORβ variants confer susceptibility to these neurodevelopmental disorders are unknown but may involve aberrant neural circuit formation and hyperexcitability during development." (PMID 37300435, 2023). "Within the region, the RORB gene is a strong candidate gene for complex neurodevelopmental disorders." (PMID 40692708, 2025).
neurological disorders (5 papers, 2012 to 2024). "Moreover, some of the candidate genes have previously been linked to psychiatric and neurological disorders (e.g. RORB, HAP1, HCRTR1 and CABP1), further emphasising the potential importance of these candidate genes in the human brain." (PMID 22384057, 2012). "Importantly, other IN genes such as Rorα and Rorβ are potential targets of MiR34/449, so whether MiR34/449 miRNAs regulate a battery of spinal INs and if disruption of those pathways account for diverse neurological disorders are interesting topics for further study." (PMID 33787491, 2021).
retinopathy (1 paper, 2022). "We hypothesize that CABP4 and RORB might be involved in the interaction of NK cells and photoreceptor cells, which can be influenced by B7 expression and might participate in symptoms associated with UVM, like retinopathy or loss of photoreceptor." (PMID 36311731, 2022).
RORB also shares sentences with these, for which no sentence is quoted: absence seizures (2 papers); developmental delay (2); microdeletion syndrome (2); speech delay (2); advanced sleep phase syndrome (1); amyloid (1); Ataxia (1); attention deficit-hyperactivity disorder (1); autosomal dominant disease (1); bipolar I disorder (1); blood pressure (1); cannabis dependence (1); cardiovascular disease (1); childhood absence epilepsy (1); colon cancer (1); cortical dysplasia (1); depression (1); Hyperhidrosis (1); idiopathic generalized epilepsy (1); insomnia (1); lymphoma (1); melanoma (1); oral squamous cell carcinoma (1); partial epilepsy (1); pharyngeal cancer (1); psychiatric disorder (1); psychosis (1); rectal cancer (1); tongue cancer (1); type 2 diabetes (1).
A further 1 disease shares a sentence with RORB in 1 paper.